BRAF (B-Raf proto-oncogene, serine/threonine kinase)
Diseases named in the same sentence as BRAF in open-access papers (continued):
Sharing a sentence is not in itself a finding about the gene and the disease.
lung carcinoma (continued). "For example, TRAF1 promoted tumor invasion of lung cancer by modulating the v-Raf murine sarcoma viral oncogene homolog B (BRAF)/mitogen-activated protein kinase kinase (MEK)/extracellular signal-regulated kinase (ERK) signaling." (PMID 40121492, 2025). "The aim of the current study is to investigate the prevalence of alterations in the eight most frequently altered genes in lung cancer—BRAF, EGFR, KRAS, ALK, ROS1, HER2, PD-L1 and PIK3CA." (PMID 41153394, 2025). "Current approved targeted inhibitors for BRAF driven lung cancers include dabrafenib and vemurafenib, which are only effective toward p.V600E mutation." (PMID 40591555, 2025). "A high rate of intratumoral heterogeneity is also common for ALK rearrangements in lung cancer, PTEN deletion in prostate cancer, as well as BRAF mutation in pulmonary adenocarcinoma." (PMID 40227771, 2025). "Tobacco is a major carcinogen linked to lung cancer, but other genetic triggers, particularly mutations in KRAS, EGFR, ALK, BRAF, RET, MET and ROS1, are also central to its development." (PMID 40556802, 2025). "In KRAS- and BRAF-driven lung cancer models, dietary supplementation with NAC and vitamin E reduced ROS levels and oxidative DNA damage in tumors." (PMID 40646353, 2025). "The same analysis reported the common features of the associated lung cancer, including the adenocarcinoma pathology and at least one driver mutation in nearly half of the cases, including KRAS, EGFR, ALK, BRAF, and ATM." (PMID 41476748, 2025). "Our study, leveraging liquid biopsy technology, successfully extended these prior findings by enabling the analysis of a larger patient cohort to provide a more comprehensive understanding of the genomic landscape of BRAF alterations in lung cancer." (PMID 41282105, 2025). "Ultrasound imaging highlighted tumor development on the left lung surface, and proteomic analysis identified specific biomarkers associated with lung cancer, such as ADAMTS12, BRAF, BRCA2, and TIF1α." (PMID 40584122, 2025). "This case underscores the challenges in treating BRAF K601E-mutant lung carcinoma, emphasizing the need for advanced molecular diagnostics, personalized approaches, and further research into more effective therapies for unique genetic profiles." (PMID 39040442, 2024). "Our study provides, for the first time, insights into the real‐world utilization of EGFR, ALK, and BRAF inhibitors in the therapy of lung cancer patients in Germany." (PMID 39693368, 2024). "According to the multi‐institutional lung cancer genomic screening project (LC‐SCRUM‐Asia), BRAF mutations are detected in 3.5% of all non‐small cell lung cancer cases." (PMID 39139611, 2024). "Anaplastic lymphoma kinase (ALK), epidermal growth factor receptor (EGFR), ROS proto-oncogene 1 (ROS1), and serine/threonine-protein kinase B-Raf (BRAF) inhibitors have become key components of lung cancer therapy." (PMID 38785748, 2024). "The 2018 CAP/AMP/IASLC (College of American Pathologists/Association of Molecular Pathology/International Association for the Study of Lung Cancer) guidelines advocated testing for EGFR, ALK, ROS1, and BRAF upfront." (PMID 39834530, 2024). "Mutations in genes encoding components of this pathway, such as KRAS, BRAF, and MEK, are commonly found in lung cancer patients." (PMID 39544928, 2024). "Several biomarkers (such as EGFR, BRAF, KRAS gene mutations, etc.)have emerged as predictive and prognostic markers for lung cancer." (PMID 38730722, 2024).
lung carcinoma (continued). "Despite BRAF gene mutations in lung carcinoma being identified before EML4-ALK translocations, there have been few clinical studies completed on this type of lung carcinoma with BRAF mutation." (PMID 39199653, 2024). "Currently, there are FDA-approved targeted therapies for lung cancers with mutations and genomic alterations in EGFR, ALK, ROS-1, NTRK, MET, RET, HER2, and BRAF." (PMID 39272844, 2024). "The management of lung cancer (LC) requires the analysis of a diverse spectrum of molecular targets, including kinase activating mutations in EGFR, ERBB2 (HER2), BRAF and MET oncogenes, KRAS G12C substitutions, and ALK, ROS1, RET and NTRK1-3 gene fusions." (PMID 38966170, 2024). "Despite these advancements, notable challenges persist whenn utilizing BRAF and MEK inhibitors for the management of BRAF mutant-driven lung cancer." (PMID 38731852, 2024). "The importance of autophagy in the initiation and/or progression of KRAS- or BRAF-driven lung cancer was revealed through analysis of GEM models in which deletion of key autophagy genes (Atg5 or Atg7) accompanied the initiation of oncoprotein expression." (PMID 39213022, 2024). "ZEB1 is also downstream of RAS and BRAF in lung carcinomas and melanomas and mediates some of the signaling of oncogenic RAS in lung carcinomas." (PMID 37870961, 2023). "To explore the potential anti-tumor targets of apatinib, we have examined all tyrosine kinases and important silk/threonine kinases associated with lung cancer including Akt 1-3, FRAP1, PIK3C2A, PIK3C2B, BRAF, BRAF V600E and RAF1 in the Life platform." (PMID 36759818, 2023). "Dysregulation of receptor tyrosine kinase (RTK) signaling leads to lung cancer, such as activating EGFR mutations are present in 15% of NSCLC, BRAF and KRAS always also mutated in lung cancer." (PMID 37061730, 2023). "As our understanding of the molecular biology of lung cancer increases, many mutated targets are being identified, including the epidermal growth factor receptor (EGFR), anaplastic lymphoma kinase, ROS1, BRAF V600E mutation, etc." (PMID 36716088, 2023). "These require local validation and implementation for clinical diagnostic purposes, similar to what has been previously done for several other actionable mutations in different tumor types (e.g., EGFR in lung cancer, BRAF in melanoma and lung cancer, etc.)." (PMID 36825198, 2023). "For patients with BRAF-mutated NSCLC, an uncommon form of lung cancer treatment options is limited and data on their efficacy and safety are scarce." (PMID 35592617, 2022). "Another mechanism of adaptation is found in defiance of MEK1/2 inhibitors, inhibitor‐treated colorectal, and lung cancer cell lines displayed intrachromosomal amplification of mutant Kras or BRAF or upregulation of upstream RTK signaling." (PMID 35398967, 2022). "This is particularly urgent in lung cancer, where mutations in EGFR, ALK, ROS, RET, METex14 skipping, BRAF, and KRAS should be identified before initial treatment." (PMID 35862868, 2022). "A previous study in 36,813 Chinese lung cancer patients, focusing on eight key lung cancer driver genes (EGFR, ALK, MET, KRAS, ERBB2, ROS1, RET, and BRAF), revealed a prevalence of 0.03% for P/LP germline mutations." (PMID 35428225, 2022). "This study intends to explore the efficacy of targeted therapy for BRAF non-V600E mutant lung cancer, and provide a reference for clinical treatment." (PMID 35224961, 2022). "Collect the relevant literature relevant on the targeted therapy of BRAF non-V600E mutant lung cancer, and conduct a descriptive analysis of the included literature." (PMID 35224961, 2022). "For example, Osimertinib is used for EGFR-driven lung cancers, whereas Dabrafenib with Trametinib is used for BRAF-driven lung cancers." (PMID 35845436, 2022).
lung carcinoma (continued). "Based on this first report of BRAF A598-T599insV mutation occurring in lung cancer, we discuss resistance mechanisms to ALK TKIs, implications of BRAF mutation in NSCLC, and BRAF A598-T599insV mutation in other cancers." (PMID 36419902, 2022). "Results from genetically engineered mouse models (GEMMs) of lung cancer, pancreatic cancer and melanoma induced by mutations in RAS or BRAF indicated that autophagy inhibited the growth of early benign tumors, but accelerated the growth of advanced cancers." (PMID 35600411, 2022). "On the other hand, similar to ALK and ROS1 fusion-positive lung cancers, patients with NTRK fusion also can develop off-target resistance to TKI therapy, mechanisms including MET amplification, BRAF V600E mutation, or hotspot mutations involving KRAS." (PMID 36508072, 2022). "There have been few case reports of long-term survival in BRAF-positive lung cancer, and more cases need to be accumulated in the future to gather more information." (PMID 35464513, 2022). "Non-small-cell lung cancer (NSCLC) is the most common subtype of lung cancer, of which approximate 4% had BRAF activation, with an option for targeted therapy." (PMID 35912223, 2022). "Compared to the TCGA data, the Nanjing Lung Cancer Cohort (NJLCC) and CHOICE cohort of Chinese patients revealed higher rates of EGFR and RB1 mutations, and lower rates of KRAS, BRAF, and STK11 mutations, in adenocarcinoma patients." (PMID 34195081, 2021). "Our group has recently profiled a large Nova Scotian lung cancer patient cohort for major driver mutations in lung cancer (EGFR, ALK, KRAS, BRAF, and PIK3CA)." (PMID 33956842, 2021). "Several combination therapies have been proposed for BRAF resistance in EGFR-mutant lung cancer, but an integrated genomic analysis of these tumors is lacking and precludes an optimization of therapeutic regimen." (PMID 34921211, 2021). "In lung cancer, the MAPK pathway is driven by oncogenic mutations (e.g., BRAF and RAS mutations), RET-PTC, and in some cases by the recently discovered ALK mutations." (PMID 33628588, 2021). "Dabrafenib and trametinib therapy for BRAF V600E‐mutant non‐small cell lung cancer (NSCLC) has demonstrated strong antitumor effects in clinical trials and has been approved for use in clinical practice." (PMID 33215864, 2021). "Most recently, the combination of the BRAF V600E specific inhibitor dabrafenib and the MEK inhibitor trametinib was approved for the treatment of BRAF V600E positive lung cancer based on a phase II study showing PFS of 14.6 months and response rate of 64%." (PMID 32131760, 2020). "ARHGEF19 is a RhoGEF that reportedly activates the MAPK pathway and interacts with BRAF in lung cancer." (PMID 33322675, 2020). "Lung cancer is well established as a highly heterogeneous tumor that harbors various gene alterations including mutations in EGFR, KRAS, BRAF, PD-L1, and PIK3CA, as well as ALK rearrangement and HER2 amplification." (PMID 33411683, 2020). "BRAF mutation occurred in 0.5–2% of Chinese NSCLC patients, which was lower than 2–5% in Caucasian lung cancers." (PMID 32411601, 2020). "Of these mutations, 97.8% (1583/1616) were found in lung cancer, with 96.71% (1530/1583) of the mutations in lung cancer were located in EGFR, 1.1% (17/1583) located in ERBB2, 0.7% (12/1583) located in BRAF, and 1.4% (23/1583) in MAP2K1." (PMID 32757330, 2020). "Currently, lung cancers are screened for actionable mutations, to identify cases suitable for targeted therapies, including those targeting mutations in EGFR, BRAF and rearrangements in ALK or ROS1." (PMID 32898185, 2020). "Despite this advancement, further treatment optimization is still required to improve the success of BRAF target therapy for lung cancers." (PMID 33037234, 2020).
lung carcinoma (continued). "Last, two lung function variants mapped to genes somatically mutated in lung cancer: EML4 (rs12466981: PFEV1/FVC = 2.7 × 10−14) and BRAF (rs13227429: PFVC = 5.6 × 10−9)." (PMID 31911640, 2020). "There are multiple other driver mutations that have been identified in lung cancer that have effective targeted therapies, including ROS1, BRAF, and NTRK mutations to name a few." (PMID 32756609, 2020). "Advances in DNA sequencing technology revealed the driver mutations in lung cancers at the genes including EGFR, ROS1, BRAF, ALK, and KRAS." (PMID 33276627, 2020). "Through gene sequencing, it can be seen that lung cancer-related genes such as epidermal growth factor receptor gene mutation, c-MET, ROS1, KRAS, and BRAF, play an extremely important role in diagnosis and treatment of lung cancer." (PMID 32316985, 2020). "This case report raises awareness among clinicians treating patients with lung cancer for the possibility of triggering a flare of autoimmune diseases like GPA in patients with BRAF V600E positive lung cancer receiving treatment with BRAF directed therapy." (PMID 32131760, 2020). "For example, non–small cell lung cancer genotyping requires mutation pattern analysis of KRAS, EGFR, and BRAF." (PMID 32329738, 2020). "The recent identification of driver oncogenes, such as EGFR, ALK, ROS1, and BRAF has already been successfully translated into clinical practice for individuals with lung cancer." (PMID 31142054, 2019). "Next-generation sequencing (NGS) and other technical improvements have revealed that 50%-80% of BRAF alterations in lung cancer are non-V600 and have considerably different signaling properties." (PMID 31533235, 2019). "In an internal review of collective Target Selector results of patients with lung cancer, slightly over 20% had KRAS exon 2 mutations and more than 20% showed activating mutations, whereas only 1.69% of patients had BRAF mutations." (PMID 31581267, 2019). "A lung cancer mouse model by inducible expression of BRAF V600E in the lung epithelial compartment led to development of lung adenocarcinoma in vivo." (PMID 31234388, 2019). "One of the important driver gene mutations, which leads to signaling pathway dysregulation in lung cancer, occurs in v-raf murine sarcoma viral oncogenes homolog B1 (BRAF)." (PMID 31234388, 2019). "In BRAF wild-type lung cancer preclinical models, the biological active properties of single or combined therapies for BRAF (dabrafenib), pan-RAF (RAF265), MEK (trametinib), and EGFR/HER2 (lapatinib) were evaluated." (PMID 31652660, 2019). "Meanwhile, for the case BRAF non-V600E mutant lung cancer models, a disabled kinase signaling transduction was observed, where EGFR has the capacity to activate the MAPK cascade." (PMID 31652660, 2019). "In this lung cancer model, TRAF1 affects TRAF2-mediated K48-linked ubiquitination and degradation of BRAF, and thereby promotes the survival and proliferation of lung cancer cells." (PMID 30294322, 2018). "In the H1755 non-V600 BRAF mutant lung cancer cell line vemurafenib and trametinib combination treatment caused a small but significant increase in apoptosis when compared to either single agent." (PMID 29739364, 2018). "The present study compared the effects of Dabrafenib and a type II RAF inhibitor, AZ628, on ERK activity in HEK293T cells expressing several tumor-derived BRAF mutants, and in a non-V600 and impaired-kinase BRAF-mutant lung cancer cell line (H1666)." (PMID 29662630, 2018). "It was reported that overall response rate with BRAF therapy was 53% and disease control rate was 85% in BRAF-mutant lung cancer." (PMID 29416679, 2018).
lung carcinoma (continued). "Knocking down TRAF1 expression in human lung cancer cell lines impaired phosphorylation of the oncogene serine/threonine-protein kinase, BRAF, and affected TRAF2-mediated BRAF Lys48-linked ubiquitination." (PMID 30619326, 2018). "We recently showed in a large series of lung cancer patients that besides allowing the identification of EGFR, KRAS, and BRAF mutations, NGS identified a potential driver in 36% of patients (FGFR, ERBB2, AKT, MAP2K1, STK11...)." (PMID 29890761, 2018). "For example, BRAF inhibitors are being currently tested or have already been approved for multiple cancer types, including lung cancer, ovarian cancer, and thyroid cancer." (PMID 30341300, 2018). "And in a mouse model of lung cancer, LKB1 loss was thought as a risk factor concomitant with BRAF V600E mutation leading to the tumor development." (PMID 29371951, 2017). "We have found that KEAP1 loss modulates sensitivity to inhibition of EGFR, ALK, BRAF, or MEK in lung cancer cell lines with EGFR, ALK, BRAF, KRAS, or NRAS mutations." (PMID 28145866, 2017). "This study provides a basis for the clinical exploration of non-V600 BRAF mutant lung cancers upon treatment with Trametinib and Dabrafenib." (PMID 28947956, 2017). "BRAF and MEK inhibitors are currently being tested in clinical trials for RAS- and BRAF-mutant lung cancer." (PMID 28145866, 2017). "MEK inhibitors are currently being tested in clinical trials for efficacy in RAS or BRAF mutant lung cancer." (PMID 27922010, 2016). "MEK inhibitors are currently in clinical development for a variety of cancers, including lung cancer, with mutations specifically in the oncogene RAS or its downstream signalling components (for example, BRAF), which occur in a large number of cancers." (PMID 27922010, 2016). "In a study with the largest series of patients with BRAF mutant lung cancers, most patients were identified to be heavy smokers." (PMID 26102513, 2015). "Next, we performed a target sequencing analysis using the Human Lung Cancer Panel (Qiagen, Hilden, Germany), which targets 20 lung cancer-related genes including most of the exons in BRAF, using the same samples." (PMID 26376781, 2015). "Jointly, our results suggest a potential role of the novel BRAF fusion in lung cancer development and therapy." (PMID 25985019, 2015). "One study in the literature described a BRAF V600E-mutant lung cancer patient responding to vemurafenib and two studies described a response to dabrafenib." (PMID 25621040, 2015). "To conclude, in this study we report the frequency of EGFR mutations in a cohort of 956 lung cancer patients as well as the frequency of alterations in KRAS, BRAF, MET, PIK3CA and ALK genes in a subset of these patients." (PMID 26208325, 2015). "With the development of molecular subtype in lung cancer, NSCLC patients with EGFR-WT had been identified to carry several new “driver mutations”, including KRAS, HER2, and BRAF mutations, as well as ALK, ROS1, and RET gene fusion." (PMID 25277203, 2014). "EGFR, KRAS, and BRAF mutations and EGFR antibody treatment (colorectal carcinoma) and EGFR inhibitor treatment (lung carcinoma) serve as good examples." (PMID 24764475, 2013). "In lung cancer patients, EGFR mutations are generally exclusive with KRAS and BRAF mutations, and tumors with either KRAS (15–25%) or BRAF (2-3%) mutations are relatively insensitive to EGFR TKIs." (PMID 22970367, 2012). "Lung cancer adenocarcinomas are predominantly associated with the following: Kirsten rat sarcoma viral oncogene homolog (KRAS - 32%); epidermal grow factor receptor (11%), and V-Raf murine sarcoma viral oncogene homolog B (BRAF - 7%) driver mutations." (PMID 39955067, 2025). "Specifically, among the 51,783 lung cancer patients with detectable ctDNA, 2,398 patients (4.63%) had tumors with non-overlapping BRAF mutations belonging to one of the three functional classes (Class I, II, or III only)." (PMID 41282105, 2025).